TLR2 (toll like receptor 2)
Diseases named in the same sentence as TLR2 in open-access papers (continued):
Sharing a sentence is not in itself a finding about the gene and the disease.
COVID-19 (continued). "Proteomic analysis showed changes in signal pathways including JAK-STAT signaling, toll-like receptor TLR1/TLR2 cascade, NFκB phosphorylation, activation of IKKs complex and MHC class II antigen presentation in the COVID-19 brains." (PMID 36609561, 2023). "In severe COVID-19, the transcriptome of whole blood shows more mRNA of several TLRs, including TLR2 and the TLR adaptor protein MyD88 in severe COVID-19." (PMID 35204803, 2022). "NRP-1 mRNA expression level had a significant positive (p = 0.000) correlation with both TLR2 and TLR4 mRNA expressions in moderate COVID-19 patients." (PMID 35891270, 2022). "We found that virus-free extracellular COVID-19 EVs induced robust NET formation via Syk-coupled C-type lectin member 5A (CLEC5A) and TLR2." (PMID 35820906, 2022). "The TLR2 and TLR4 mRNA expression levels were significantly higher (p < 0.01) in moderate and severe COVID-19 groups than in the healthy control group." (PMID 35891270, 2022). "Blockade of CLEC5A inhibited COVID-19 EVs-induced NETosis, and simultaneous blockade of CLEC5A and TLR2 further suppressed SARS-CoV-2-induced NETosis in vitro." (PMID 35820906, 2022). "As observed in gene expression results, the expression of TLR2/MyD88 and NOX4/Nrf2 was also overexpressed in COVID-19 patients." (PMID 36498845, 2022). "In the current study, TLR2 and TLR4 showed significantly higher expression in the blood of moderate and severe COVID-19 patients than in healthy individuals." (PMID 35891270, 2022). "It is thought that the production of proinflammatory cytokines is induced by the activation of different TLRs, such as TLR2, TLR4, and TLR7/8, which greatly contributes to the pathogenesis of COVID-19 and its severity." (PMID 35832809, 2022). "In this study, we further demonstrated that COVID-19 EVs express abundant markers of activated platelets, enhance NET formation via CLEC5A and TLR2." (PMID 35820906, 2022). "This work clearly demonstrates that PLT-EVs from COVID-19 patients can enhance thromboinflammation via CLEC5A and TLR2, and further shows that PLT-EVs from virus-activated act as endogenous danger signals to cause systemic inflammation." (PMID 35820906, 2022). "Parallel to the expression of MyD88, the expression of TLR1, TLR2, TLR4, TLR5, TLR8 and TLR9 was significantly elevated in patients with severe and critical COVID-19." (PMID 35682644, 2022). "Here we report that COVID-19 EVs express abundant markers of activated platelets, and induce NET formation via CLEC5A and TLR2." (PMID 35820906, 2022). "ACE2 mRNA expression level exhibited a significant positive (p = 0.000) correlation with both TLR2 and TLR4 mRNA expressions in the severe COVID-19 group." (PMID 35891270, 2022). "In the context of COVID-19, using our method, we were able to identify VCAN and TLR2 as potential targets for immunomodulatory attempts, which was further confirmed by analyzing two independent patients with severe symptomatology." (PMID 33536217, 2021). "In the present study, we also found high expression of both TLR2 and TLR4 genes in peripheral blood leukocytes of severe COVID-19 cases." (PMID 33345622, 2021). "The fold change or relative expression of TLR-2, TLR-4, and PGRP-4 was significantly higher in COVID-19 saliva as compared to that in the control saliva." (PMID 34707585, 2021). "In particular, the S protein increases TLR2 in CD14+ macrophages, and the S protein is correlated with a high level of TLR2 in cells derived from patients with COVID-19." (PMID 34360684, 2021). "For example, in severe COVID-19, TLR7 (viral) and TLR4 (bacterial/fungal) synergize, TLR9 and TLR4 (both bacterial/fungal) synergize and TLR2 and TLR4 (both bacterial/fungal) synergize with NLRP3 (viral and bacterial)." (PMID 33672738, 2021). "Elevated levels of TLRs such as TLR2 and Toll-Like Receptor 4 (TLR4), alongside increased expression of the Nuclear Factor Kappa B (NF-κB) transcription factor, were observed more so in severe compared to moderate COVID-19 patients." (PMID 39928675, 2025).
COVID-19 (continued). "When compared to a control group of SARS-CoV-2 (−) negative lungs (COVID-19−), TLR-2 expression was up-regulated in a subset of patients with deadly COVID-19 fatal lung illness." (PMID 38786077, 2024). "On the other hand, activation of TLRs such as TLR2, TLR4, and TLR7/8 leads to the release of proinflammatory cytokines by cells, a phenomenon which studies have shown to largely determine the development of complications in COVID-19." (PMID 39457048, 2024). "Interestingly, the activation of TLR2 in the immunodominant cytotoxic T lymphocyte response to the spike glycoprotein of SARS-CoV-2, which is also produced by COVID-19 vaccines, was described." (PMID 36366292, 2022). "Therefore, the analysis of the genotypes of TLR2, TLR3, TLR4, TLR6, TLR7, TLR8, and TLR9 is important for the study of COVID-19." (PMID 35327350, 2022). "TLR2 and TLR4 sense viral proteins, and the expression levels of molecules related to the TLR2- and TLR4-inflammatory signaling molecules are upregulated in in COVID-19 patients, which suggest the involvement of TLR2 and TLR4 signaling in the induction of pathological inflammation during COVID-19." (PMID 35832809, 2022). "As COVID-19 sera was reported to induce NET formation, and serum levels of platelet-derived EVs (PLT-EVs) correlated with disease severity, we asked whether COVID-19 EVs induced NET formation was via CLEC5A and TLR2." (PMID 35820906, 2022). "The combination of SARS-CoV-2 S-E-M proteins activates TLR2 signaling increasing Nf-κB/ERK1/2 and inflammasome activation, which is attenuated by NAC, suggesting a plausible explanation of the beneficial effects of NAC observed in COVID-19 patients." (PMID 36498845, 2022). "Our study concluded that impaired renal and cardiac biomarkers might be attributed to increased expression levels of TLR2, TLR4, ACE2, and NRP-1 mRNA in both moderate and severe COVID-19 patients." (PMID 35891270, 2022). "Furthermore, SARS-CoV-2 and COVID-19 EVs induced NET formation via CLEC5A and TLR2, and clec5a−/−tlr2−/− mice were resistant to SARS-CoV-2-induced lung inflammation and collagen deposition." (PMID 35820906, 2022). "Zheng and colleagues reanalyzed the expression of MyD88 and TLRs in patients with different severity grades of COVID-19 using a public dataset and found that the expression of MyD88, TLR1, TLR2, TLR4, TLR5, TLR8, and TLR9 was increased in patients with severe to critical illness." (PMID 34834939, 2021). "Additionally, the heat shock protein HSP5a (also known as GRP78), a marker for endoplasmic reticulum stress and the TLR2/TLR4 activator, is released at unusually high concentrations in severe COVID-19 patients." (PMID 33672738, 2021). "The molecular mechanisms triggered by the binding of the S protein to its cellular receptors, such as ACE2, TLR2/4, NRP1, DPP4, and CD147, among others, across various tissues and organs, provide valuable insights and are essential in understanding the pathophysiology of both COVID-19 and LC." (PMID 40431631, 2025). "Taken together, these data suggest that the interaction of rSP with TLR2 and TLR4 on NK cells may have a strong impact on the immunopathology of COVID-19 and provides a clue that such receptors and/or their intracellular pathways could represent potential therapeutic targets." (PMID 38881905, 2024). "Besides high activity of the NF-κB pathway, our signalling analysis showed engagement of the EBV pathway in BALF MΦ from patients with severe COVID-19, which is characterized by CD21−, CD19−and MHC-II dependent entry mechanisms, and by a TLR2-MyD88 dependent additional activation of NF-κB." (PMID 38034686, 2023). "In conclusion, low secretion of IL-8 was observed upon stimulation with TLR2, TLR4, TLR7/8, TLR9, and NOD2 agonists by the blood cells of COVID-19 patients at hospital admission and was restored after two weeks of hospitalization, which may be a contributing factor to immunosuppression." (PMID 37189696, 2023).
COVID-19 (continued). "Also, higher levels of both TLR2 and TLR6 genes were observed with the severity of COVID-19." (PMID 35573725, 2022). "Thus, TLR2 and TLR4 could be possible targets to prevent the severity of COVID-19 and develop therapeutic strategies for the disease." (PMID 35891270, 2022). "Moreover, TLR2 inhibition protects against SARS-CoV-2–induced lethality in K18-human angiotensin-converting enzyme 2 (K18-hACE2) transgenic mice, indicating that TLR2 contributes to disease progression in COVID-19." (PMID 36419185, 2022). "However, increased levels of TLR2 with either TLR1 or TLR6 DAMPs, including beta-defensin-3, named TLR1/2, and the high-mobility group box-1 (HMGB1), named TLR1/2/6, were recorded in peripheral blood mononuclear cells and serum obtained from COVID-19 patients." (PMID 34770863, 2021). "In addition, GRP78 has been identified as a DAMP for specific TLRs (TLR2 and TLR3) and may account for promotion of augmented inflammation in COVID-19 patients." (PMID 33498183, 2021). "The recent discovery of MMG11 (a TLR2 inhibitor, which shows preference for the TLR1/2 heterodimer) and CuCpt22 (a TLR1/2 heterodimer inhibitor in mice and a TLR1/2/6 inhibitor in humans) may represent potential COVID-19 therapeutics." (PMID 33498183, 2021). "However, data about the role of the TLR2 rs3804099 SNP in COVID-19 is lacking." (PMID 38703289, 2024). "In summary, the response of TLR4 and of TLR2 to SARS-CoV-2 may switch the anti-viral response of the lung from the release of type I IFNs to an exaggerated synthesis of pro-inflammatory mediators, explaining at least in part the hyperinflammation observed in severe COVID-19." (PMID 38034686, 2023). "The highest expression levels are found for Cathepsin L, followed by TLR4/MD-2 and TLR2 on macrophages and endothelial cells, whereas ~10fold lower expression levels are seen for TLR1, 6, and 7, which may correlate with the different pathophysiological relevance in COVID-19, as discussed later." (PMID 35682644, 2022). "While we note that other Toll-like immune receptors such as TLR-2, -4, -5, -7 and -8 may be stimulated by the COVID-19 virus, they were not considered here as their exact roles are not established, with some possibly functioning even to the advantage of the coronavirus." (PMID 33257716, 2020). "Severity and disease progression in patients with COVID-19 was shown to correlate with the expression of MyD88, i.e., a key adaptor molecule in TLR-signaling, and the expression of TLR1, TLR2, TLR4, TLR5, TLR8 and TLR9 (but not TLR3)." (PMID 38791489, 2024). "While EVs from healthy control were unable to induce NET formation, COVID-19 EVs induced robust NET formation, which was blocked efficiently by anti-CLEC5A mAb, but not anti-TLR2 mAb." (PMID 35820906, 2022). "In addition, an elegant study has recently shown that S protein signals through TLR2 and activates the NLRP3 (NLR family pyrin domain containing 3) inflammasome in human macrophages obtained from convalescent patients with COVID-19, but not from healthy SARS-CoV-2–naïve individuals." (PMID 36112681, 2022).
periodontitis (98 papers, 2008 to 2026). An acute or chronic inflammatory process that affects the tissues that surround and support the teeth. "A meta-analysis revealed that the TLR2 Arg677Trp polymorphism was associated with an increased risk of severe periodontitis, confirming its role in modulating the immune response to oral pathogens." (PMID 41295183, 2025). "HGF expresses TLR2, 4, and 5 for a critical role in immune response, principally faces and interacts with pathogenic invasion at an early stage of periodontitis." (PMID 35437426, 2022). "It should be mentioned that other studies reported a significantly higher bone loss and a more severe degree of periodontitis in TLR-2-deficient mice than in wild-type mice." (PMID 32714091, 2020). "In recent years, a number of studies have shown that multiple immune gene polymorphisms are associated with the susceptibility to periodontitis, among which TLR-2 plays a critical role in periodontitis." (PMID 32831974, 2020). "Several animal studies with different periodontitis models showed that TLR-2-deficient mice exhibit lower levels of alveolar bone loss and proinflammatory cytokine expression compared to wild-type and TLR-4-deficient mice." (PMID 32714091, 2020). "The objective of this study was to investigate the potential value of salivary sTLR-2 and sTLR-4 together with the paired epithelial cell-associated TLR-2/4 mRNA as diagnostic markers for chronic periodontitis." (PMID 30571680, 2018). "In the present study, we investigated the effects of GM-0111 on molecular events associated with periodontitis, ranging from the anti-inflammatory effects mediated by TLR2 and TLR4, RANKL-induced osteoclast formation, and pathogenic bacterial growth." (PMID 27308827, 2016). "On the other hand, it has been shown that TLR2 is crucial for inflammatory bone loss in an experimental model of periodontitis induced by infection with P. gingivalis." (PMID 22723864, 2012). "Moreover, periodontitis was associated with an enhanced production of TLR2, MyD88 and TGFβ, as well as higher activities of SOD and catalase antioxidant enzymes in the adipose tissue." (PMID 42037322, 2026). "Furthermore, increased methylation of the TLR2 promoter has been reported in a mouse model of periodontitis caused by infection with Porphyromonas gingivalis." (PMID 33671221, 2021). "Significant association was found between periodontitis and TLR-2 rs1898830 polymorphism under the allelic model (A allele vs. G allele: p = 0.014, OR = 1.208, 95% CI: 1.039-1.406), recessive model (GG vs. GA+AA: p = 0.028, OR = 0.755, 95% CI: 0.588-0.970), and codominant model (GG VS." (PMID 32831974, 2020). "Therefore, the meta-analysis and subgroup analysis further clarify the relationship between TLR2 polymorphism and periodontitis susceptibility in order to reconcile inconsistencies across individual studies." (PMID 32831974, 2020). "Furthermore, the essential role of TLR-2 in periodontitis-associated tissue destruction was demonstrated in multiple in vivo studies." (PMID 32714091, 2020). "Interestingly, although numerous studies have demonstrated a link between TLR-2 and periodontitis susceptibility, focusing on certain SNPs like rs5743708 and rs1898830, they showed no positive conclusion from their findings." (PMID 32831974, 2020). "In subgroup analysis, TLR-2 rs5743708 polymorphism was associated with periodontitis risk in Asians under an allelic model (G allele vs. A allele: p = 0.017, OR = 12.064, 95% CI: 1.570-92.688), dominant model (GA+AA vs.GG: p = 0.016, OR = 0.08, 95% CI: 0.010-0.620), and codominant model (GA VS." (PMID 32831974, 2020). "Interestingly, TLR2 is required for P. gingivalis-induced inflammatory bone loss in experimental periodontitis in mice." (PMID 31848404, 2019). "Several studies indicate an association between periodontitis progression and TLR-2." (PMID 31178663, 2019).
periodontitis (continued). "The enhanced expression of TLRs in the periodontium with periodontitis, as well as significant contribution of TLR2 to alveolar bone loss suggest that the inhibitory effects of GM-0111 on TLRs may provide a therapeutic benefit in periodontitis." (PMID 27308827, 2016). "In the present study, we investigated whether GM-0111 disrupts events associated with periodontitis such as the growth and biofilm formation of P. gingivalis, TLR2/TLR4-mediated cellular activation and osteoclast formation in vitro." (PMID 27308827, 2016). "It is, therefore, suggested that elevated gene expressions for IL-1B and TLR2 may constitute a common risk factor for periodontitis and RA." (PMID 25657893, 2015). "Furthermore, direct microbial interaction with immune cells may underlie this, as loss of Toll-like receptor-2 (TLR2) in antigen-presenting cells reduces IL-17 secretion from Th17 cells that dysregulate the host immune system in periodontitis." (PMID 34884490, 2021). "For example, it has been reported that tissue affected by periodontitis and normal periodontal tissue show differences in the methylation status of promoters for inflammation-related genes such as those encoding interleukin (IL)-8, tumor necrosis factor-alpha (TNFα) and toll-like receptor-2 (TLR2)." (PMID 33671221, 2021). "The TLR-2 rs1898830, rs5743708 polymorphism may be associated with susceptibility to periodontitis." (PMID 32831974, 2020). "At baseline, TNF-α and TLR-2 levels were significantly higher in periodontitis patients compared with healthy controls (p < 0.001)." (PMID 42154854, 2026). "In this study, IHC assays further demonstrated that P. gingivalis increased Tlr2, Tlr4 and Myd88 expression in P. gingivalis-induced mouse periodontitis compared with that in the controls." (PMID 40307566, 2025). "In another study, hypermethylation and silencing of the TLR2 gene in tissues with periodontitis were confirmed, and the authors found a correlation between the methylation status of the TLR2 gene and probing depths." (PMID 38740675, 2024). "SAA is elevated in serum of periodontitis patients and increased in inflamed gingival tissues where it triggers inflammatory cytokines via a TLR2 pathway." (PMID 38098978, 2023). "Starting with a report that the methylation of CpG sites in the promoter of IFNγ was significantly higher in the gingiva of periodontitis patients, methylation of TLR2 promoter, TNF-α promoter, and others were reported to be associated with periodontitis." (PMID 36294882, 2022). "Elevated expression of toll-like receptor 2 and toll-like receptor 4 is found in gingival tissue biopsies from patients with DM and periodontitis compared with patients with periodontitis alone." (PMID 35694215, 2022). "Among them, MYOM2 and TLR2 genes were significantly upregulated in patients with periodontitis in comparison to healthy controls (p = 0.032 and p = 0.003, respectively), confirmed by RT-PCR." (PMID 36233348, 2022). "A study conducted by de Faria Amormino and co-workers observed hypermethylated TLR2 gene profiles in gingival biopsies of chronic periodontitis patients, correlated with probing depth parameters and quantity of inflammatory cells." (PMID 36291079, 2022). "As shown in TLR‐2 deficient mice, activation of TLR‐2 is furthermore crucial in mediating bone loss in periodontitis." (PMID 32474936, 2021). "The activation of TLR2/4 signaling is positively associated with the progression of T2DM and periodontitis." (PMID 34401982, 2021). "Several polymorphisms were associated with periodontitis, including the Fc-γ receptor, ILs-1,4,6,10,18, TNF-α, vitamin D receptor, cluster of differentiation-14, MMP-1, Toll-like receptor-2 and 4, and COX-2." (PMID 33340075, 2021). "Recently, case-control studies on the significance of the SNP rs5743708 in the TLR2 gene in periodontitis were summarized in a meta-analysis." (PMID 34305452, 2021).